Y_RNA (Y RNA )
Gene: Miscellaneous RNA gene on chromosome 8 (94,713,715 to 94,713,812, reverse strand). Ensembl gene ENSG00000199701.
Homologues: Orthologues: chimpanzee Y_RNA (96% identical), macaque Y_RNA (96% identical). Paralogues in human: Y_RNA (90% identical), Y_RNA (88% identical), RNY3 (87% identical), RNY3P14 (87% identical), Y_RNA (87% identical), Y_RNA (86% identical), Y_RNA (85% identical), RNY3P1 (84% identical), Y_RNA (84% identical), RNY3P2 (83% identical), Y_RNA (83% identical), RNY3P11 (82% identical), and 92 more.